RPAP1 (RNA polymerase II associated protein 1)
Description:
Forms an interface between the RNA polymerase II enzyme and chaperone/scaffolding protein, suggesting that it is required to connect RNA polymerase II to regulators of protein complex formation. Required for interaction of the RNA polymerase II complex with acetylated histone H3.
Synonyms: KIAA1403; DKFZP727M111; MGC858; FLJ12732
Tractability: PROTAC: ubiquitination databases record sites on it; its protein half-life has been measured.
Gene: Protein-coding gene on chromosome 15 (41,517,176 to 41,544,278, reverse strand). Ensembl gene ENSG00000103932.
Subcellular location: Nucleus
Subcellular location (Human Protein Atlas): Nucleoplasm; Cytosol
Gene Ontology:
Molecular function: protein binding
Biological process: transcription by RNA polymerase II
Cellular component: nucleus
Genetic constraint (gnomAD): Loss-of-function variants: 107 observed, 143.35 expected, observed/expected ratio (o/e) 0.75, 90% interval 0.64 to 0.88. The upper end of that interval is the gene's LOEUF score, 0.88, which puts it in group 3 of 6, group 1 being the genes least tolerant of losing a copy. Missense variants: 1,527 observed, 1,758.2 expected, observed/expected ratio (o/e) 0.87, 90% interval 0.83 to 0.91. Synonymous variants: 700 observed, 744.71 expected, observed/expected ratio (o/e) 0.94, 90% interval 0.88 to 1.
Homologues: Orthologues: chimpanzee RPAP1 (99% identical), macaque RPAP1 (88% identical), pig RPAP1 (85% identical), rabbit RPAP1 (84% identical), dog RPAP1 (84% identical), guinea pig RPAP1 (82% identical), mouse Rpap1 (80% identical), rat Rpap1 (80% identical), tropical clawed frog rpap1 (50% identical), zebrafish rpap1 (46% identical), Drosophila melanogaster CG32104 (23% identical).
Diseases named in the same sentence as RPAP1 in open-access papers:
RPAP1 is named in the same sentence as 4 diseases in open-access papers, as found by Europe PMC text mining. Sharing a sentence is not in itself a finding about the gene and the disease. The quoted sentences say what the papers report.
breast carcinoma (1 paper, 2014). "Of these, two SNP pairs (APEX1-rs1130409 *RPAP1-rs2297381 and MLH1-rs1799977 *MDM2-rs769412) showed the strongest statistical association with breast cancer (P<7.3×10−3), with modest FDR values of 0.30 and 0.49, respectively." (PMID 23755158, 2014). "We observed two two-way SNP-SNP interactions (APEX1-rs1130409 and RPAP1-rs2297381; MLH1-rs1799977 and MDM2-rs769412) in logistic regression that conferred elevated risks for breast cancer (Pinteraction<7.3×10−3)." (PMID 23755158, 2014).
sporotrichosis (1 paper, 2021). The commonest and least serious of the deep mycoses, characterized by nodular lesions of the cutaneous and subcutaneous tissues. "Next, we assessed the potential of the polyclonal anti-rHsp60 and anti-rPap1 to protect against experimental systemic sporotrichosis." (PMID 34829247, 2021). "Our results are in line with these observations, since the polyclonal antibodies anti-rHsp60 and anti-rPap1 were capable of protecting against systemic sporotrichosis, suggesting that both Hsp60 and Pap1 are adhesins that have a major contribution to S. schenckii virulence." (PMID 34829247, 2021).
infection (2 papers, 2021 to 2023). The state of being infected such as from the introduction of a foreign agent such as serum, vaccine, antigenic substance or organism. "When S. schenckii cells were inoculated into G. mellonella larvae, both rHsp60 and rPap1 conferred protection against experimental infection, suggesting that they are adhesins that make an important contribution to the virulence of this species." (PMID 37623561, 2023).
cancer (1 paper, 2023). A tumor composed of atypical neoplastic, often pleomorphic cells that invade other tissues. "There are no relevant reports of ZNF79, PRICKLE3, RPAP1, ABHD8, and FBXO33 in cancer, and more research is still needed." (PMID 37274025, 2023).